IGF2BP2 (insulin like growth factor 2 mRNA binding protein 2)
Diseases named in the same sentence as IGF2BP2 in open-access papers (continued):
Sharing a sentence is not in itself a finding about the gene and the disease.
liver cirrhosis (3 papers, 2018 to 2025). "The presence of IGF2BP2 in liver cirrhosis suggests that this RBP is generated during pathological alterations before liver transformation." (PMID 29736175, 2018). "Autoantibody against p62 was found in 21% of HCC patients but completely absent in chronic hepatitis and liver cirrhosis, suggesting that the autoimmune response to IGF2BP2 is associated with transformation." (PMID 29736175, 2018). "Encouragingly, the combination of IGF2BP2 and alanine aminotransferase (ALT) demonstrated efficacy in predicting the presence of liver cirrhosis, as determined by receiver operating characteristic (ROC) analysis." (PMID 38443347, 2024). "Later characterization showed that IGF2BP2 was expressed in scattered cells in liver cirrhosis nodules but present in all cells in HCC nodules, confirming the upregulation of IGF2BP2 with hepatocellular transformation." (PMID 29736175, 2018).
metaplastic carcinoma of the breast (3 papers, 2020 to 2023). "In addition, IGF2BP2 was regulated by CCN6 protein in metaplastic carcinomas of the breast." (PMID 34608837, 2021).
psoriasis (3 papers, 2022 to 2025). An autoimmune condition characterized by red, well-delineated plaques with silvery scales that are usually on the extensor surfaces and scalp. "The results of single‐cell RNA sequencing in the lesions of psoriasis patients and RNA sequencing in BMDMs revealed that YTHDF1 and IGF2BP2 were expressed in macrophages." (PMID 40679079, 2025). "RT-qPCR results in the skin specimen showed that YTHDC2 was highly expressed in the psoriasis and IMQ group compared to the controls, while METTL3 and IGF2BP2 were decreased in the disease group, which was consistent with the results in GSE30999." (PMID 38436011, 2024). "Our experiments verified that the mRNA level of YTHDC2 was elevated in psoriasis patients, and the expression of METTL3 and IGF2BP2 was significantly decreased." (PMID 38436011, 2024).
renal fibrosis (3 papers, 2023 to 2025). A final common manifestation of a wide variety of chronic kidney diseases characterized by glomerulosclerosis and tubulointerstitial fibrosis. "In summary, our findings demonstrate that multiple prefibrotic stimuli lead to significant upregulation of MELTT3 in TECs and kidney tissues, which enhances the m6A modification of EVL mRNA via an IGF2BP2‐dependent mechanism, ultimately contributing to the advancement of renal fibrosis." (PMID 37537731, 2023). "In summary, our study provides the first evidence that circUBXN7/IGF2BP2/SP1 formed RNA-protein complex, which improves mRNA stability of SP1 and the expression of SP1, promoting macrophage infiltration and renal fibrosis, accelerating the progression of DKD." (PMID 37744330, 2023).
squamous cell carcinoma (3 papers, 2018 to 2025). A carcinoma arising from squamous epithelial cells. "According to the semi-quantitative results of IHC, we found that the expression of IGF2BP2 increased gradually in epithelial hyperplasia, epithelial dysplasia and squamous cell carcinoma (SCC) (all P<0.01)." (PMID 36793593, 2023).
ulcerative colitis (3 papers, 2021 to 2025). An inflammatory bowel disease involving the mucosal surface of the large intestine and rectum. "We found that IGF2BP1 and IGF2BP2 expression was decreased in Crohn’s disease (CD) tissues and that IGF2BP2 was decreased in ulcerative colitis (UC) tissues compared with normal tissues (P < 0.05)." (PMID 34422815, 2021).
Abdominal obesity (2 papers, 2011 to 2019). Excessive fat around the stomach and abdomen. "In CTRF+ individuals, mRNA levels of TSPAN8 associated with T2D family history (p < 0.01), of IGF2BP2 tv7 with serum glucose levels, while in the total group of controls, KCNQ1 tv1 levels reversely with BMI, central obesity, glucose and LDL (mg/dl) levels (p < 0.05)." (PMID 30728419, 2019).
asthma (2 papers, 2021 to 2025). "This indicates that IGF2BP2 facilitates M2 macrophage polarization, hence intensifying allergic inflammation in asthma." (PMID 41008562, 2025). "With respect to IGF2BP2 deficiency in hematopoietic cells, following CRE treatment, IGF2BP2–/– mice reconstituted with WT bone marrow cells (WT →IGF2BP2–/–) exhibited asthma signs as severe as those in wild‐type mice (WT → WT)." (PMID 34258163, 2021). "Moreover, the expression of IGF2BP2 was detected in asthmatic and it was mostly colocalized with macrophages in human asthma samples." (PMID 34258163, 2021). "Additionally, the m6A RNA modification machinery including METTL3, METTL14, FTO, YTHDF1/2, IGF2BP2, and WTAP is explored for its emerging significance in regulating post-transcriptional gene expression during asthma progression." (PMID 41008562, 2025).
atherosclerosis (2 papers, 2022 to 2024). A disease characterized by the build-up of fatty material and calcium deposition in the arterial wall resulting in partial or complete occlusion of the arterial lumen. "RT‐qPCR and western blotting results indicated that compared with the Control group, IGF2BP2 mRNA and protein levels in the aortas of mice in the atherosclerosis group were significantly increased (p < .05)." (PMID 39432244, 2024). "Therefore, binding of the reader IGF2BP2 to H19 regulated its expression in the animal and cell models of atherosclerosis." (PMID 39432244, 2024).
bladder urothelial carcinoma (2 papers, 2021 to 2024). "UALCAN database showed that IGF2BP2 was highly expressed in bladder urothelial carcinoma (BLCA) tissues." (PMID 39014364, 2024).
cervical squamous cell carcinoma (2 papers, 2022 to 2024). A squamous cell carcinoma arising from the cervical epithelium. "When any of the m6A readers (IGF2BP2 and IGF2BP3) or m6A writer METTL3 were mutated, BRD9 was significantly highly expressed in cervical squamous cell carcinoma and endocervical adenocarcinoma (CESC), BRCA and LUAD." (PMID 38303608, 2024). "The results showed that the expressions of WTAP were downregulated; and the expressions of four m6A-RMRs such as HNRNPA2B1, IGF2BP2, FMR1, and HNRNPC were upregulated in patients with preinvasive and invasive cervical squamous cell carcinomas compared with normal controls." (PMID 35211628, 2022).
colon adenocarcinoma (2 papers, 2021 to 2022). "According to the database analysis, the profiles of IGF2BP2 and TUG1 are positively relevant in both Colon adenocarcinoma (COAD) or Rectum adenocarcinoma (READ), which means they may well interact with each other in CRC." (PMID 35014946, 2022).
depression (2 papers, 2016 to 2021). "We found 224 upregulated and 284 downregulated genes, including genes previously found to be associated with depression such as CXCL10 (FC=+2.13) and insulin-like growth factor 2 mRNA binding protein 2 (IGF2BP2, FC=+1.88)." (PMID 27067128, 2016).
endometriosis (2 papers, 2022 to 2023). The growth of functional endometrial tissue in anatomic sites outside the uterine body. "This research has demonstrated that some m6A regulators, such as METTL3, FTO, and IGF2BP2, participate in the process and development of endometriosis, while there are few studies on other m6A regulators." (PMID 36672827, 2022). "Recent studies have proved that m6A methylation transferase methyltransferase like 3 (METTL3) might play a key role in the development of endometriosis, while the other two m6A regulators, FTO and IGF2BP2, have also been reported to participate." (PMID 36672827, 2022).
hyperglycaemia (2 papers, 2020 to 2023). "IGF2BP2 variations were also associated with decreased insulin secretion and hyperglycemia." (PMID 32329795, 2020).
kidney papillary carcinoma (2 papers, 2021 to 2025). "Finally, in kidney papillary carcinoma (KIRP), the signature included YTHDC2, IGF2BP2, DNMT3B, TRMT6, HNRNPC, and NSUN5." (PMID 40565233, 2025).
nonalcoholic steatohepatitis (2 papers, 2021 to 2022). "IGF2BP2 up-regulates the expression of fatty acid elongase 6 (ELOVL6), which catalyzes the elongation of C16 fatty acids to C18, contributing to the development of human nonalcoholic steatohepatitis." (PMID 33568150, 2021).
periodontitis (2 papers, 2025). An acute or chronic inflammatory process that affects the tissues that surround and support the teeth. "The same trend was found for IL-1β, IL-6, and TNF-α, thereby suggesting a role for IGF2BP2 in the regulation of inflammation in periodontitis." (PMID 39629934, 2025). "IGF2BP2 expression was also found in high levels in alveolar bone, periodontal ligament, and gingival tissue from patients with periodontitis." (PMID 39629934, 2025). "Using a ligature-induced periodontitis murine model increased the level of IGF2BP2 found at 3 d in alveolar bone, and the expression decreased after 14 d." (PMID 39629934, 2025). "Similarly, findings have demonstrated the role of IGF2BP2 in the regulation of both inflammatory response and osteoclast differentiation in periodontitis." (PMID 39629934, 2025).
polycystic ovary syndrome (2 papers, 2024). A disorder that manifests as multiple cysts on the ovaries. "Analysis of the association between IGF2BP2 and IGFBP3 polymorphisms and the risk of polycystic ovary syndrome (PCOS) was carried out on a total of 300 subjects using both ARMS‐PCR and PCR‐RFLP methods." (PMID 38468402, 2024).
prediabetes (2 papers, 2019 to 2024). "Another study found a strong correlation between IGF2BP2 rs11705701 and prediabetes in the Chinese population." (PMID 38468402, 2024).
primary immunodeficiency (2 papers, 2021 to 2022). "“Cell cycle”, “ECM receptor interaction”, “focal adhesion”, and “pathways in cancer” were the enriched KEGG gene sets in the high IGF2BP2 expression group, whereas “primary immunodeficiency” was enriched in the low IGF2BP2 expression group." (PMID 35299748, 2022).
renal cell carcinoma (2 papers, 2023). "ZNF677, which plays a tumor suppressor role in renal cell carcinoma, can be stabilized by METLL3/IGF2BP2-regulated m6A modification at the post-transcription level." (PMID 37280679, 2023). "SHMT2 improves the m6A abundance of PPAT mRNA by offering methyl donor SAM, allowing IGF2BP2 to enhance the stability and expression of PPAT, regulating cell cycle to promote proliferation in renal cell carcinoma." (PMID 37280679, 2023).
schizophrenia (2 papers, 2021 to 2025). A major psychotic disorder characterized by abnormalities in the perception or expression of reality. "The IGF2BP2 polymorphisms are associated with vulnerability to schizophrenia in a Han Chinese population and with impaired pancreatic β-cell function, including lower fasting insulin levels, which reduced glucose-stimulated insulin secretion." (PMID 33315097, 2021). "Extensive research has highlighted the significant role of genes, including genes such as 5-HTR2C, CHRNA, IGF2BP2, and TPH, in the susceptibility of patients with schizophrenia to comorbid T2D." (PMID 39857704, 2025). "Other candidate genes, such as insulin like growth factor 2 mRNA binding protein 2 (IGF2BP2) or transcription factor 7 like 2 (TCF7L2), may also contribute to the genetic basis of the co-occurrence of schizophrenia and T2DM." (PMID 33315097, 2021).
testicular cancer (2 papers, 2018 to 2023). A primary or metastatic malignant neoplasm that affects the testis. "A few studies have also shown the association of IGF2BP2 with other malignancies, including prostate, ovarian, and testicular cancer." (PMID 29736175, 2018). "In terms of mechanisms, LncRNA MALAT1 contributed to testicular cancer progression through the upregulation of IGF2BP2 by binding to miR-204." (PMID 37365581, 2023). "While IGF2BP1 was detected in all carcinomas, IGF2BP2 and IGF2BP3 were only seen in a subset of testicular cancers." (PMID 29736175, 2018).
type 1 diabetes (2 papers, 2012 to 2021). "Additionally, IGF2BP2 was found to be downregulated and linked to diabetic nephropathy in male patients with type 1 diabetes (T1D), as well as impaired glucose tolerance in patients with type 2 diabetes (T2D)." (PMID 34869344, 2021).
acute kidney injury (1 paper, 2023). Sudden and sustained deterioration of the kidney function characterized by decreased glomerular filtration rate, increased serum creatinine or oliguria. "Inhibition of METTL3 obviously alleviates renal injury and inflammation through IGF2BP2-dependent mechanisms, which suggests that targeting METTL3 may be a promising therapeutic approach for acute kidney injury (AKI)." (PMID 37006311, 2023).
adrenocortical carcinoma (1 paper, 2022). "IGF2BP2 is downregulated in several tumours, including breast‐invasive carcinoma, adrenocortical carcinoma, pheochromocytoma and ccRCC according to TCGA database." (PMID 35876041, 2022).
allergic asthma (1 paper, 2021). A asthma with a basis in a pathological type I hypersensitivity reaction. "Conversely, IGF2BP2 deficiency ameliorated CRE induced allergic asthma, and knockout of IGF2BP2 constrained M2 macrophages polarization." (PMID 34258163, 2021).
Allergy (1 paper, 2021). An allergy is an immune response or reaction to substances that are usually not harmful. "Together, our new identification of the master role of IGF2BP2 in macrophages differentiation may help to further understand the pathophysiological function of m6A modifications in many macrophage‐directed sites, including inflammation, allergy, and tumor progression." (PMID 34258163, 2021).
astrocytoma (1 paper, 2022). "In a single-cell RNA-seq analysis of astrocytoma dataset, 23 out of 28 m6A-RMRs (82%) (except ALKBH5, IGF2BP1, IGF2BP2, IGF2BP3, and G3BP2) were in the medium to high expression levels in malignant cells of astrocytoma." (PMID 35211628, 2022).
cardiac hypertrophy (1 paper, 2022). "Several m6A “readers” might impede cardiac hypertrophy such as YTHDF2 and IGF2BP2." (PMID 35571209, 2022).
cardiac ischemia (1 paper, 2023). "Strikingly, IGF2BP2 is upregulated not only in mouse models of cardiac ischemia and pressure overload but also in human patients with dilated cardiomyopathy and after myocardial infarction." (PMID 38052926, 2023).
cataract (1 paper, 2019). Partial or complete opacity of the crystalline lens of one or both eyes that decreases visual acuity and eventually results in blindness. "In CC54, 5 genes (ANAPC1, RPIA, IGF2BP2, CYP2J2 and LRIG1) and 1 disease (Cataract) were extracted as a correlated set." (PMID 31345171, 2019).
Cerebral arteriovenous malformation (1 paper, 2024). "IGF2BP2 is significantly downregulated in cerebral arteriovenous malformations (AVMs), reducing LGALS8 mRNA stability through m6A modification, thereby severely impairing brain vascular development in vivo." (PMID 39722688, 2024).
Cirrhosis (1 paper, 2024). A chronic disorder of the liver in which liver tissue becomes scarred and is partially replaced by regenerative nodules and fibrotic tissue resulting in loss of liver function. "In order to assess the potential utility of IGF2BP2 as a marker for cirrhosis, a total of 46 serum samples from cirrhotic patients and 24 samples from healthy individuals were collected." (PMID 38443347, 2024). "Enzyme linked immunosorbent assay (ELISA) revealed that patients with cirrhosis exhibited higher levels of IGF2BP2 in their serum." (PMID 38443347, 2024).
Cognitive impairment (1 paper, 2025). Abnormal cognition is characterized by deficits in thinking, reasoning, or remembering. "In conclusion, our current study first explored the role of IGF2BP2 in mediating neuronal pyroptosis and cognitive impairment in vitro." (PMID 39783247, 2025).
dilated cardiomyopathy (1 paper, 2023). Cardiomyopathy which is characterized by dilation and contractile dysfunction of the left and right ventricles. "To elucidate the underlying mechanisms through which IGF2BP2 helps mediate dilated cardiomyopathies, we prepared protein extracts from hearts expressing either the IGF2BP2 transgene or the Tet transactivator alone for 15 days and analyzed them by mass spectrometry (MS)." (PMID 38052926, 2023). "Having observed that hIGF2BP2 expression in mouse hearts is sufficient to cause dilated cardiomyopathy and that IGF2BP2 RNA is up-regulated in hearts that have undergone cardiac stress, we wondered whether IGF2BP2 protein expression is elevated in human pathologies." (PMID 38052926, 2023). "Enhanced expression of an IGF2BP2 transgene in a conditional, inducible mouse line leads to dilated cardiomyopathy (DCM) and death within 3-4 weeks in newborn or adult hearts." (PMID 38052926, 2023). "Consistent with the mouse data, elevated levels of IGF2BP2 are observed in human patients with dilated cardiomyopathies or after myocardial infarctions." (PMID 38052926, 2023). "The resulting dilated cardiomyopathy eventually leads to heart fatigue and death, unless IGF2BP2 expression is reduced in time." (PMID 38052926, 2023). "Furthermore, activating IGF2BP2 expression in either newborn or adult transgenic mice results in dilated cardiomyopathy leading to heart failure or cardiac dysfunction and precocious death within 3–4 weeks after induction of expression." (PMID 38052926, 2023). "Heart-specific overexpression of the RNA binding protein IGF2BP2 leads to dilated cardiomyopathy (DCM) and death in mice that can be rescued if downregulated in time, suggesting that IGF2BP2 could be a target for therapeutic intervention in DCM." (PMID 38052926, 2023).
endometrial tumour (1 paper, 2018). "Loss of IGF2BP2 staining, which is a feature of endometrioid cancers, but not serous cancers, has been proposed as a biomarker for distinguishing endometrial tumour pathology." (PMID 30513694, 2018).
escherichia coli infection (1 paper, 2020). Infection with the organism Escherichia Coli. "In the pathway analysis of genes that were positively related to IGF2BP2 expression, the top three enriched terms were as follows: salmonella infection, shigellosis and pathogenic Escherichia coli infection." (PMID 33246429, 2020).
fibrosis (1 paper, 2022). the formation of excess fibrous connective tissue in an organ or tissue in a reparative or reactive process. "In a mouse model where IGF2BP2 was instead upregulated in the liver by the transgene, lipid storage was enhanced, which led to fibrosis and NAFLD." (PMID 35163144, 2022).
heart failure (1 paper, 2023). Inability of the heart to pump blood at an adequate rate to meet tissue metabolic requirements. "This response, however, comes at the price of impaired mitochondria and reduced sarcomere organization that eventually leads to heart failure (cardiac dysfunction) if IGF2BP2 levels are not reduced." (PMID 38052926, 2023).
human papillomavirus infection (1 paper, 2020). "In the KEGG pathway analysis of genes that were positively related to IGF2BP2 expression, the top three enriched terms were as follows: human papillomavirus infection, endocytosis and salmonella infection." (PMID 33246429, 2020).
hyperlipidemia (1 paper, 2019). "Additionally, in T2D individuals, the levels of THADA tv5 correlated reversely with hyperlipidemia and those of IGF2BP2 tv7 positively with BMI (p < 0.05)." (PMID 30728419, 2019).
hyperuricemia (1 paper, 2025). An abnormally high level of uric acid. "Our study provides the first evidence that METTL3 regulates uric acid excretion by controlling the m6A levels of ABCG2 through the binding of IGF2BP2, and inhibiting METTL3 can effectively alleviate kidney damage caused by hyperuricemia, showing potential as a therapy for HN." (PMID 40100069, 2025).